GDNF (glial cell derived neurotrophic factor)
Diseases named in the same sentence as GDNF in open-access papers (continued):
Sharing a sentence is not in itself a finding about the gene and the disease.
renal agenesis (12 papers, 2010 to 2024). Renal agenesis (RA) is a form of renal tract malformation characterized by the complete absence of development of one or both kidneys (unilateral RA or bilateral RA respectively), accompanied by absent ureter(s). "Furthermore, many other mutant genes that cause renal agenesis exert their effects via the GDNF/RET pathway." (PMID 20084103, 2010). "Similar to GDNF deletion, loss of ITGA8 in mouse leads to impaired UB outgrowth in the MM and results in renal agenesis." (PMID 38563997, 2024). "GDNF deletion in mice results in significant defects in UB outgrowth and consequently renal agenesis." (PMID 38563997, 2024). "Another study demonstrated that stillborn fetuses with renal agenesis or severe dysplasia had a high positive rate (30%) of disease-causing mutations, although only RET, GDNF, and GFRA1 genes were evaluated." (PMID 32164334, 2020). "While mutations in either gene had no discernible effect on kidney development, double mutant mice presented renal agenesis and/or severe renal hypoplasia; hence Etv4 and Etv5 account for the profound effects of GDNF signaling during kidney development." (PMID 30483151, 2018). "GDNF in mice disturbs the invasion and induces renal agenesis of variable manifestation Our in vivo study found that under hyperglycemic condition, ureteric bud invasion of metanephric mesenchyme is defective." (PMID 23468876, 2013). "For instance, Six1 knockout mice display renal agenesis despite apparently normal levels of GDNF mRNA." (PMID 24143282, 2013). "Deletion of upstream mediators of GDNF expression, such as Eya1, Pax2, and Gdf11, also results in renal agenesis." (PMID 24143282, 2013). "Ret and GDNF (as well as the GDNF co-receptor Gfrα1) play a critical role in UB branching morphogenesis, and their absence leads to renal agenesis in mice and humans." (PMID 21060807, 2010). "In the kidney, GDNF expression is associated with epithelial differentiation of the nephrogenic mesenchyme, and the absence of this gene results in renal aplasia or severe hypodysplasia." (PMID 33413640, 2021). "When Spry1 is absent there is no brake on signaling via FGFR2, and GDNF can be removed without causing renal agenesis, due (at least in part) to the effects of FGF10, and to the restoration of Etv4/Etv5 expression; however, UB branching pattern is abnormal." (PMID 20084103, 2010). "Next to the detrimental phenotypes provided by loss of GDNF or ITGA8, alterations in kidney development do not always have to result in renal agenesis but can affect the final kidney size and number of nephrons and glomeruli." (PMID 38563997, 2024). "Indeed, mouse models with null mutations in Ret or Gfrα1 demonstrated that signaling through GDNF-RET-GFRα1 is critical for kidney development, as these mice also present renal agenesis or severe renal hypoplasia." (PMID 30483151, 2018). "Genetic manipulations such as noninducible knocking-out of Ret or GDNF in mice results in renal agenesis or severe hypodysplasia, limiting our ability to use these tools to generate mice with low nephron number and simulate renal consequences of human preterm birth." (PMID 36626229, 2023).
cognitive decline (11 papers, 2015 to 2026). "The effects of GDNF on neuronal atrophy, a condition associated with cognitive decline in old age, were investigated in another study." (PMID 35360515, 2022). "In addition, GDNF expression was linked to cognitive decline, and direct mechanistic pathways connecting GDNF malfunction and ASD pathology warrant further investigation." (PMID 39502974, 2024). "Further research is required to clarify BDNF dynamics and to determine GDNF's role in motor progression and cognitive decline." (PMID 41697575, 2026). "Another potential mechanism is that GDNF may counteract neuronal degeneration and delay the onset of cognitive decline." (PMID 39513043, 2024). "All in all, GDNF might be used as a biomarker to identify early cognitive decline in PD, and might serve in clinical practice." (PMID 36908789, 2023).
renal fibrosis (10 papers, 2013 to 2025). A final common manifestation of a wide variety of chronic kidney diseases characterized by glomerulosclerosis and tubulointerstitial fibrosis. "A similar study demonstrated that GDNF‐modified ADSCs released GDNF‐rich exosomes, which could be transferred to renal fibrosis tissues and ameliorate peritubular capillary loss via the activation of the SIRT1/eNOS signaling pathway." (PMID 35441482, 2022). "Thus, the activation of the SIRT1/eNOS pathway may be the underlying mechanism by which GDNF-AMSC-exos enhance PTC density to protect against renal fibrosis." (PMID 32802201, 2020). "In a UUO mouse model, Chen et al152 reported that ASC-Exos transfected with glial cell-derived neurotrophic factor (GDNF) ameliorated renal fibrosis by activating the SIRT1/eNOS signaling pathway." (PMID 39263535, 2024). "In a UUO renal fibrosis model, GDNF-overexpressing hADMSC-EVs exhibited higher potency to reduce peritubular capillary rarefaction and renal fibrosis score/α-SMA levels than native EVs." (PMID 36341339, 2022). "A significant reduction in renal fibrosis in mice was also demonstrated after administration of ASCs overexpressing glial cell line-derived neurotrophic factor (GDNF) or exosomes derived from GDNF-transfected ASCs." (PMID 34685439, 2021). "The role of GDNF-AMSC treatment in renal fibrosis is demonstrated in vitro and in vivo, which is a significant step before the clinical translation of the GDNF-AMSCs." (PMID 33413640, 2021). "In summary, our study identified the ability of exosomes isolated from GDNF-AMSCs in ameliorating renal fibrosis." (PMID 32802201, 2020). "In summary, obese nephron-deficient GDNF HET mice were able to maintain the high creatinine clearances of obese WT mice but at the expense of higher MAP and greater renal fibrosis." (PMID 24019901, 2013). "In addition, studies have also demonstrated that GDNF expression can regulate renal microcirculation and inhibit epithelial-to-mesenchymal transition (EndMT) and renal fibrosis." (PMID 38606083, 2024). "However, GDNF, as a tissue morphogen, showed not only a better effect on mitigating renal fibrosis in vivo but also better improvement of angiogenesis and reduction of endothelial damage caused by hypoxia in vitro." (PMID 33413640, 2021). "The present study aimed to determine whether glial cell line-derived neurotrophic factor (GDNF)-modified AMSCs hold an enhanced protective effect on renal fibrosis." (PMID 33413640, 2021). "Thus, an advantage of GDNF-AMSCs in alleviating renal fibrosis may be due to its ability to increase peritubular microvasculature." (PMID 33413640, 2021). "Compared with UUO, the GFP-AMSC and GDNF-AMSC groups, especially the latter, showed less renal fibrosis." (PMID 33413640, 2021). "Our study identified that intrarenal delivery of GDNF-AMSC-exos increased the number of PTCs, decreased renal fibrosis, and upregulated SIRT1 expression." (PMID 32802201, 2020). "GDNF-AMSC-exos significantly decreased PTC rarefaction and renal fibrosis scores in mice with UUO." (PMID 32802201, 2020). "Surprisingly, the greater renal fibrosis observed in obese GDNF HET mice was not reflected in greater albuminuria as detected by ELISA." (PMID 24019901, 2013).
bipolar disorder (9 papers, 2011 to 2025). A disorder of the brain that causes unusual shifts in mood, energy, activity levels and the ability to carry out day-to-day tasks. "The results obtained agree with the data of another work, which documented an increase in GDNF in the peripheral blood of patients who have bipolar disorder in the depressive phase." (PMID 39170712, 2024). "Our recent study found that the changes in GDNF in LF of patients with bipolar disorder and MDD were similar to those found in FE and in FE + MDD in the present study." (PMID 38069144, 2023). "Findings of studies investigating peripheral GDNF levels in bipolar disorder are less consistent than those in BDNF research." (PMID 25202283, 2014). "One of the significant findings of our study is the low level of GDNF in bipolar disorder patients." (PMID 32283906, 2020). "The changes in the levels of GDNF, IGF-1 and Nrn 1 might be involved in pathopysiology of bipolar disorder, and GDNF, IGF-1 may be considered as state markers in bipolar manic episode." (PMID 32283906, 2020). "Unlike depressive episodes in MDD, which tend to be associated with a reduction of GDNF, bipolar depression does not seem to influence GDNF levels." (PMID 25202283, 2014). "Differences in methodology, patients’ age, and medication status may explain some of the discrepancies in outcomes of GDNF studies in bipolar disorder." (PMID 25202283, 2014). "Additionally, variability in GDNF findings may be a reflection of a biological heterogeneity within bipolar disorder." (PMID 25202283, 2014). "Moreover, serum neurotrophin-3, neurotrophin-4/5, and GDNF are also altered in bipolar disorder." (PMID 25202283, 2014). "Hovewer, GDNF and IGF-1 may be used as state markers and these findings will be helpful for the development of new treatment strategies which include neurotrophins for bipolar disorder in the future." (PMID 32283906, 2020). "However, there are a limited number of studies on the relationship between bipolar disorder and the level of GDNF and, there is no consensus on the results of these studies." (PMID 32283906, 2020). "Expressions of NT-3 and two members of the related family of glial cell line-derived neurotrophic factor, GDNF and ARTN, were found down-regulated in circulating blood cells of patients with MDD but not in bipolar disorder." (PMID 24222865, 2013).
prostate carcinoma (9 papers, 2015 to 2024). A carcinoma that arises from epithelial cells of the prostate gland. "We also compared GDNF transcript levels by microarray analysis in micro-dissected cancer-associated stromal tissue before and after exposure to chemotherapy in men with prostate cancer enrolled in a neoadjuvant clinical trial combining mitoxantrone and docetaxel." (PMID 25575823, 2015). "For example, this occurs via glial-derived neurotrophic factor (GDNF) production in prostate cancer, IL-6 in lymphoma, and exosome secretion in colorectal cancer." (PMID 36010899, 2022). "It was also shown that the other neurotrophic factor, GDNF released by prostate cancer fibroblasts was involved in docetaxel tumor chemoresistance." (PMID 34277455, 2021). "Overall we observed a growth promoting and pro-invasive influence of GDNF toward prostate cancer cells." (PMID 25575823, 2015). "Together, these data indicate that GDNF stimulation is associated with reduced RB activity and enhanced E2F1 and AR target gene expression in a subset of prostate carcinoma that are receptive to GDNF signaling by virtue of RET and/or GFRA1 receptor expression." (PMID 25575823, 2015). "The majority of prostate cancers expressed GFRA1 (82%) and all tumors showed RET expression, indicating that a majority of localized prostate cancers are potentially sensitive to GDNF." (PMID 25575823, 2015). "Together, these findings indicate that prostate cancer cells expressing GFRA1 respond to GDNF stimulation with the activation of the SRC/ERK pathway and increased mitotic rates." (PMID 25575823, 2015). "We therefore sought to determine if GDNF influenced prostate cancer phenotypes of growth, invasion, and resistance to cancer therapeutics." (PMID 25575823, 2015). "To determine the sensitivity of prostate cancer to GDNF, we exposed a spectrum of prostate cancer cell lines to GDNF and monitored cell proliferation over a period of 3-5 days." (PMID 25575823, 2015). "There was a clear correlation between GDNF sensitivity of the prostate cancer cell lines and GFRA1 expression levels which separated the four sensitive lines from the non-responsive lines." (PMID 25575823, 2015). "We report here that genotoxic treatments induce GDNF secretion in both prostate fibroblasts and bone fibroblasts, which consequently induces prostate cancer cell proliferation and treatment resistance." (PMID 25575823, 2015). "Fibroblast GDNF exerted paracrine effects toward prostate cancer cells resulting in enhanced tumor cell proliferation and invasion, and these effects were concordant with the expression of known GDNF receptors GFRA1 and RET." (PMID 25575823, 2015). "Furthermore, GDNF stimulation increased the proliferation rate of prostate cancer cells and activated the signal pathway through GFRα1/SRC pathway, which was related to the expression level of GFRα1, but not related to RET." (PMID 35582425, 2022). "Specifically, GDNF (Glial Cell Derived Neurotrophic Factor) has been hypothesized to promote tumor growth and invasion in prostate cancer and its effect of resisting treatment could be related to the expression of its receptor GFRA1." (PMID 31118022, 2019). "GDNF has treatment counter-acting effects in prostate cancer cells which may limit the efficacy of DNA damaging strategies for treating localized and advanced prostate cancers." (PMID 25575823, 2015). "The changes in cell proliferation and the activation of the SRC/ERK pathway in prostate cancer cells upon stimulation with GDNF indicated that GDNF could also have an effect on the survival of prostate cancer in the context of cancer-directed therapeutics." (PMID 25575823, 2015). "GDNF has been shown to be elevated in prostate cancer reactive tumor stroma where it is hypothesized to contribute to tumor growth and invasion." (PMID 25575823, 2015). "GDNF acted as a chemo-attractant to prostate cancer cells in our experiments." (PMID 25575823, 2015).
prostate carcinoma (continued). "Specifically, GDNF stimulation increases the proliferation rate of prostate cancer cells." (PMID 25575823, 2015). "GDNF is a major regulator of directed neurite growth, indicating that it also could have effects on the migratory and invasive behavior of prostate cancer." (PMID 25575823, 2015). "As autonomic innervation has been shown to correlate with disease progression in prostate cancer, GDNF could exert adverse indirect effects via it's known neurotrophic activities." (PMID 25575823, 2015). "The fact that GDNF reduces the sensitivity of prostate cancer to commonly used treatment regimens could further enhance this effect by increasing the pool of actively proliferating cells during and after genotoxic treatment cycles." (PMID 25575823, 2015). "However, the increase in RET activity within prostate cancers may also be attributed to increased secretion of GDNF by prostatic stromal cells or GFRα1 by peripheral nerves within the prostate, ultimately promoting perineural invasion of prostate cancers." (PMID 35957881, 2022). "Importantly, GDNF is robustly secreted by fibroblasts in the tumor environment upon treatment-induced DNA damage, which can promote prostate cancer cell proliferation and may act as a feedback mechanism contributing to treatment resistance." (PMID 30666215, 2018). "However, GDNF could have comparable trophic effects on prostate cancer cells and stromal cells as seen in neurons and other tissues, with acute effects on prostate cancer growth and treatment resistance." (PMID 25575823, 2015). "Prostate and bone stromal cells substantially increased GDNF expression and secretion following genotoxic damage, indicating that GDNF produced in the tumor microenvironment could exert effects toward prostate cancer cells at the primary site and at the predominant site of metastasis." (PMID 25575823, 2015). "GDNF and GFR α 1 are secreted by the increased nerves in the peritumoral stroma of prostate cancer to create a perineural niche where RET signaling can occur." (PMID 35582425, 2022). "GDNF-mediated RET activity also promotes cell proliferation, invasion and perineural spread in in vitro and preclinical animal models of prostate cancer and can be further enhanced in the presence of soluble forms of GFRα1 released by nerves." (PMID 30666215, 2018). "Stimulation with GDNF did not induce AKT activation in any of the prostate cancer lines analyzed (data not shown), consistent with the findings in prostate and bone stromal cells." (PMID 25575823, 2015).
spinal cord injury (9 papers, 2012 to 2024). Penetrating and non-penetrating injuries to the spinal cord resulting from traumatic external forces (e.g., WOUNDS, GUNSHOT; WHIPLASH INJURIES; etc.). "In this study, we examined the efficacy of human umbilical cord blood mononuclear cells (hUCB-MCs), genetically modified with the VEGF and GDNF genes using adenoviral vectors, on posttraumatic regeneration after transplantation into the site of spinal cord injury (SCI) in rats." (PMID 28421147, 2017). "Another work reported the application of HP thermogel in spinal cord injury (SCI) therapy, where glial cell-derived neurotrophic factor (GDNF) binding with HP endows the thermogelling system with neuroprotection function to inhibit apoptosis and proliferate neural stem cells." (PMID 34202514, 2021).
inflammatory bowel disease (8 papers, 2013 to 2025). A spectrum of small and large bowel inflammatory diseases of unknown etiology. "Scholors have found that the GDNF is expressed abnormally in inflammatory bowel disease, confirming the specific diagnostic role of GDNF for digestive system diseases." (PMID 38699694, 2024). "Furthermore, the authors reported that inflammatory bowel disease and experimental colitis were associated with a reduction in the expression of GDNF and that restoring GDNF was sufficient to inhibit the inflammation-induced compromise in the epithelial barrier both in vivo and in vitro." (PMID 37692784, 2023). "GDNF also has a strong anti‐apoptotic effect on colonic epithelial cells and is increased in mucosa of inflammatory bowel disease (IBD) patients." (PMID 32808420, 2020). "It is known that GDNF is upregulated in inflammatory bowel disease and could act to protect intestinal epithelial cells from cytokine-induced apoptosis." (PMID 37508531, 2023). "Furthermore, it was reported that GDNF was able to exert anti‐pro‐inflammation function in renal interstitial fibrosis and inflammatory bowel disease." (PMID 34826215, 2022). "Furthermore, it has also been shown, that GDNF levels are modified in inflammatory bowel diseases such as Crohn's disease and ulcerative colitis." (PMID 28152033, 2017). "Recent studies also showed that GDNF supports intestinal barrier maturation and protects against inflammation-induced damage in inflammatory bowel disease (IBD)." (PMID 40642294, 2025).
injury (8 papers, 2014 to 2023). Damage inflicted on the body as the direct or indirect result of an external force, with or without disruption of structural continuity. "Recently, Siebert and Osterhout indicated that neurotrophic factors, especially BDNF, GDNF, and NT-3, promote axonal regeneration after spinal trauma and have a profound effect on oligodendrocyte lineage cells." (PMID 37239968, 2023). "Together, these results indicate that MSCs expressing EGFP alone did not provide analgesia, whereas transplantation of MSCs engineered to secrete GDNF reduces pain behavior after nerve injury." (PMID 25888914, 2015). "Glial cell-line-derived neurotrophic factor (GDNF) can help attenuate neuropathic pain in different animal models of nerve injury." (PMID 24642655, 2014). "EVs obtained from A-MSCs were transfected with glial cell line-derived neurotrophic factor (GDNF) (GDNF-A-MSC-EVs), which is known to promote the MSC therapeutic effects in renal injury." (PMID 37376163, 2023). "We investigated the therapeutic effects of adenoviral-mediated GDNF on neuropathic pain behaviors, microglial activation, pro-inflammatory cytokine expression and programmed cell death in a chronic constriction injury (CCI) nerve injury animal model." (PMID 24642655, 2014).